ZEB1 (zinc finger E-box binding homeobox 1)
Diseases named in the same sentence as ZEB1 in open-access papers (continued):
Sharing a sentence is not in itself a finding about the gene and the disease.
pancreatic cancer (continued). "In pancreatic cancer, XIST contributes to improve cell migration, invasion, and EMT capacities by acting as a miR-429 molecular sponge to regulate ZEB1 expression." (PMID 32127028, 2020). "To this end, we turned to PANC-1 pancreatic cancer cells which have a known mesenchymal character, and express the EMT-TFs SNAIL1 and ZEB1." (PMID 32326239, 2020). "However, both studies are highly debated; a recent study from the Brabletz lab could show that genetic ablation of the EMT-activator ZEB1 in a murine pancreatic cancer model blocks invasion and metastasis, highlighting the non-redundant roles of EMT transcription factors." (PMID 32414223, 2020). "This in turn leads to ZEB1-mediated EMT induction, which contributes to gemcitabine resistance in pancreatic cancer cells." (PMID 32664703, 2020). "Interestingly, ZEB1 can also directly suppress the transcription of miR-200 family members, miR-141 and miR-200c, indicating a significant interplay between ZEB1 and miR-200 family miRNAs that contributes to the differentiation state of pancreatic cancer cells." (PMID 31080555, 2019). "Our results further show that ZEB1-activated ATM/p-CHK1-mediated DNA repair contributed to gemcitabine resistance of pancreatic cancer cells." (PMID 31783584, 2019). "In pancreatic cancer cells and mouse xenografts, EGCG alone and in combination with gemcitabine prevented the “Cadherin Switch” as well as downregulated expression of TCF8/ZEB1, Vimentin, and β-Catenin, thus reducing the mesenchymal phenotype." (PMID 31405071, 2019). "The presence of Zeb-1 and other modulators of EMT maintains drug resistance in human pancreatic cancer cells." (PMID 31514451, 2019). "The role of ZEB family is specific to cancer: ZEB1 is important in the invasion and metastasis of colon cancer, while ZEB2 is important in pancreatic cancer, gastric cancer and ovarian cancer." (PMID 30356400, 2018). "It was already demonstrated in a previous study that Zeb1-mediated EMT contributes to resistance to gemcitabine, 5-fluorouracil and cisplatin in various pancreatic cancer cell lines." (PMID 29903049, 2018). "In the primary pancreatic tumor, the Fsp1/tdTomato‐positive cancer cells with a partial EMT program were also positive for other mesenchymal markers including αSMA, vimentin, and Zeb1." (PMID 30120146, 2018). "Our data strongly suggest that linc-DYNC2H1-4 acts as a sponge of miR-145 to upregulate the expression of its targets, MMP3, Oct4, Lin28, Nanog, Sox2 and ZEB1, thereby promoting EMT progression and CSC formation in pancreatic cancer cells." (PMID 28703793, 2017). "ZEB1 can repress the expression of the miR-200 family and stemness-inhibiting miR-203, resulting in activation of EMT and tumor-initiating capacity in pancreatic cancer." (PMID 28245823, 2017). "ZEB1 can suppress the members of miR-200 family, leading to activation of EMT and maintenance of pancreatic cancer stemness." (PMID 29299179, 2017). "We also examined transcription factor expression and found that ZEB1 and Snail expression were decreased after EZH2 silencing in pancreatic cancer cell lines." (PMID 26848980, 2016). "Notch-1 signaling is an important pathway to upregulate the expression of EMT markers, ZEB1 and 2, Slug and vimentin, leading to the EMT, migration and drug resistance of pancreatic cancer cells." (PMID 27231938, 2016). "In pancreatic cancer, FoxM1 is overexpressed and promotes EMT by the up-regulation of mesenchymal cell markers such as ZEB1, ZEB2, SLUG, and vimentin." (PMID 26905733, 2016). "After restoration of miR-652, the acidity treated pancreatic cancer cells showed MET-like transformation, which was rescued by re-expression of ZEB1." (PMID 26498682, 2015).
pancreatic cancer (continued). "We next analyzed the expression of miR-652 and ZEB1 in PDAC (pancreatic ductal adenocarcinoma) and normal pancreatic tissues to further identify its roles in development of pancreatic cancer." (PMID 26498682, 2015). "We found that the generic EMT score correlates positively with the immunofluorescence staining of EMT markers such as ZEB1, VIM and metastatic ability in various pancreatic cancer cell lines." (PMID 25214461, 2014). "We also observed a subsequent reduction of miR-200 downstream targets ZEB1 and ZEB2, SNAIL and SLUG following the knockdown of DCLK1 in pancreatic tumor xenografts." (PMID 24040120, 2013). "We found that levels of ZEB1 protein inversely correlated with expression of the mir-200 family of miRNAs, but levels of ZEB1 RNA varied in both NSCLC and pancreatic cancer cells." (PMID 22045191, 2012). "Acquisition of gemcitabine-resistant phenotype of pancreatic cancer cells is accompanied by the elevated notch activity, whose silencing by siRNA attenuates the EMT phenotype such as vimentin, ZEB1, Slug, and Snail expression." (PMID 22934011, 2012). "NFκB also promotes EMT in pancreatic cancer cells by inducing mesenchymal marker Vimentin and EMT-related transcriptional factor ZEB1." (PMID 22934011, 2012). "Other studies have previously identified Zeb1, Zeb2, and Snail as central regulators of E-cadherin suppression and EMT in pancreatic cancer cells." (PMID 21887310, 2011). "The comparison of EMT-TFs expression levels between PDAC and healthy pancreatic tissue revealed significantly elevated mRNA levels of SNAI1, SNAI2, ZEB1 and TWIST in pancreatic cancer tissue, while ZEB2 expression was higher in normal pancreatic tissue (p < 0.05)." (PMID 41481650, 2026). "Similarly, we observed heterogenous expression of ZEB1 in macrophages in publicly available single cell transcriptomes of colorectal cancer (CRC) and pancreatic cancers." (PMID 40595293, 2025). "ZEB1 stimulates the ERK/MAPK signaling pathway, which further enhances pancreatic cancer invasion." (PMID 39941895, 2025). "To verify that ZEB1 regulated HMOX1, we established stable ZEB1-silenced pancreatic cancer cells." (PMID 39827156, 2025). "Interestingly, the transcription factor Zeb1 was reported to have a substantial role in EMT activation, promoting cell plasticity and metastasis in pancreatic cancer, as well as in ferroptosis, a cell death pathway induced by oxidized lipids." (PMID 41365870, 2025). "In order to shed light on the investigation between EPLIN and its reported interacting partners and mechanism behind action in pancreatic cancer, we revealed that EPLIN regulated expression level of SNAIL, SLUG and ZEB1, three important contributors to the EMT process, positively." (PMID 39730634, 2024). "Recently, it has been reported that ZIP4 promoted the development of pancreatic cancer through the zinc finger E-box binding homeobox 1 (ZEB1)/Integrin α3β1/equilibrative nucleoside transporter (ENT1) 1,2 and zona occludens 1 (ZO-1)/claudin-1/ZEB1 pathways." (PMID 39040931, 2024). "Moreover, ZEB1 can also recruit NuRD complex, which contains HDAC1/2, to promote the EMT and tumor progression in pancreatic cancer and lung cancer." (PMID 35601657, 2022). "Indeed, inhibition of the EMT activator ZEB1 by the HDAC inhibitor mocetinostat has been shown to impede drug resistance to oncotherapy in lung and pancreatic cancer." (PMID 35601657, 2022). "The level of expression of another EMT-related transcription factor, ZEB1, did not change in pancreatic cancer cell lines after the downregulation of SOX9." (PMID 35884771, 2022).
pancreatic cancer (continued). "Also, compared to the control group, pretreatment TMG significantly enhanced ZEB1, O-GlcNAcylation, and FADS2 protein expression levels in the subcutaneous pancreatic carcinoma tissues." (PMID 35844792, 2022). "In order to determine whether ZEB1 can regulate the expression pattern of LINC00472 in the progression of pancreatic cancer, we further examined the expression pattern of ZEB1 in the pancreatic cancer tissues and adjacent normal tissues by RT‐qPCR." (PMID 34363438, 2021). "There is direct in vivo evidence that, e.g., the lack of Zeb1 expression in a genetic mouse model of pancreatic cancer that traps the cancer cells in an epithelial phenotype profoundly suppresses invasion and metastasis." (PMID 34459003, 2021). "For this, we tested mouse pancreatic cancer cell lines derived from a Pdx1-cre;KrasLSL.G12D/+;Tp53LSL.R172H/+ mouse model (KPC), which has been further modified to obtain the Zeb1 knockout, called KPCZ, to show a role of Zeb1 in the metastatic cascade of pancreatic tumors." (PMID 33654197, 2021). "In contrast, downregulated miRNA-150 expression has been identified in lymphoma, acute myeloid leukemia, pancreatic cancer, esophageal squamous, colorectal cancer (CRC), and hepatocellular carcinoma, where miRNA-150 targets several oncogenes such as Akt, MUC4, ZEB1, and c-Myb." (PMID 33848981, 2021). "Functional analysis showed that NR3C2 may inhibit pancreatic cancer cell metastasis by reducing EMT, with an induction in E-cadherin and a decrease in ZEB1, N-cadherin, and vimentin." (PMID 34249704, 2021). "Namely, such an experimental approach has elucidated a negative feedback loop between Zeb1 and two members of the miRNA-200 family (miRNA-200c and miRNA-141) that triggers the invasive potential of pancreatic cancer cells." (PMID 34771695, 2021). "HDAC1/2 are recruited to ZEB1 on CDH1 promoter, inducing its repression in pancreatic cancer cells." (PMID 33803458, 2021). "EGCG inhibited MIA PaCa-2 and Panc-1 pancreatic cancer migration and invasion in vitro and in vivo through modulation of EMT demonstrated via the prevention of cadherin switch as well as a decrease in TCF8/ZEB1, β-Catenin and vimentin expression." (PMID 32521759, 2020). "While miR-200c-3p and miR-217 induce MALAT1 RNA degradation, MALAT1 suppresses miR-200c-3p and miR-217 function and miR-217 translocation from the nucleus to the cytoplasm, up-regulates ZEB1 and KRAS expression, and induces pancreatic cancer cell migration and invasion." (PMID 32174966, 2020). "Given the fundamental role of ZEB1 as a prime element of a network of transcription factors that controls EMT, the miR-675/UBQLN1 axis was shown to regulate the progression and development of pancreatic cancer by the regulation of ZEB1-dependent EMT." (PMID 32549375, 2020). "Western blot and qRT-PCR confirmed that miR-128 could regulate ZEB1 and further inhibit CD47 in pancreatic cancer cells." (PMID 32536914, 2020). "Lower levels of AKR1B1 was seen in mice with pancreatic tumours after knockdown of ZEB1 in comparison with controls; however, no direct effect was found between AKR1B1 and ZEB1 suggesting an indirect interaction." (PMID 32633024, 2020). "And the interaction of ITGB4 promoter with some transcription factors in other disease is also reported, such as KLF4 in glioma 21, RUNX1 in myeloid leukemia 22, ZEB1 in prostate cancer 23, TP73 in lung cancer 24, GLI1 in ovarian cancer 25, and JUN in pancreatic cancer." (PMID 31602273, 2019). "This suppression, mediated by ZEB1, promoted cell survival and EMT in pancreatic cancer cell lines." (PMID 30542509, 2018). "In the context of pancreatic cancer, lineage tracing studies revealed fibroblast‐specific protein‐1 (Fsp1, also called S100A4), Zeb1, and Snail‐expressing cancer cells, defined as cancer cells exhibiting a partial EMT program, were observed early in tumor formation." (PMID 30120146, 2018).
pancreatic cancer (continued). "Furthermore, over-expression of Notch-1 has been found led to the acquisition of EMT phenotype by up-regulation of mesenchymal cell markers, ZEB1, ZEB2, Snail2, and down-regulation of epithelial cell marker, E-cadherin, in pancreatic cancer cells." (PMID 29202800, 2017). "In pancreatic cancer, the EMT-activator, Zeb1, maintains stemness of cells, in part, through Bmi1." (PMID 26023734, 2015). "Additionally, ZEB1 can down-regulate E-cadherin expression via recruiting histone deacetylases HDAC1 and HDAC2 in pancreatic cancer." (PMID 26036631, 2015). "In accordance with previous observations we detected ZEB1 in all analyzed pancreatic cancers only in the stromal compartment but not in epithelial cells." (PMID 25910082, 2015). "In line with this hypothesis, the inhibition of ZEB1 reverted EMT and restored drug sensitivity in pancreatic cancer cells lines." (PMID 24213498, 2012). "ZEB1 is a transcription factor required for the induction of EMT, and the expression ZEB1 protein is a suitable marker for EMT, because ZEB1 is not expressed in normal pancreatic tissue, but strongly in pancreatic carcinoma." (PMID 23227088, 2012). "Interestingly, Zeb1 was primarily responsible for the acquisition of an EMT phenotype, along with increased migration and invasion in response to NF-κB signaling in pancreatic cancer cells." (PMID 24281219, 2010). "Additionally, we observed that ZEB1 overexpression is contingent upon the overexpression of SNAI1, indicating a regulatory cascade where SNAI1 enhances the expression of ZEB1, further promoting invasive and metastatic behavior of pancreatic cancer cells." (PMID 41481650, 2026). "Thus, the combination of activation of the KLF5/ZEB1/HMOX1 axis and oxaliplatin may provide a potential therapeutic strategy for pancreatic cancer." (PMID 39827156, 2025). "Under gemcitabine treatment, a chemoresistant clone expressing EMT properties could be selected by inhibiting expression of the gemcitabine transporter ENT1 in pancreatic cancer cells via solute carrier family 39 member 4 (SLC39A4, also called ZIP4)-ZEB1 pathway." (PMID 37173915, 2023). "Furthermore, miRNAs belonging to the miR-200 family, such as miR-200a, play a role in regulating stemness in pancreatic cancer by reducing the expression of CSC markers and EMT-related genes such as CD24, CD44, EpCAM, as well as the EMT markers N-cadherin, ZEB1, and vimentin." (PMID 38139352, 2023). "Therefore, overexpression of LOXL2 and ZEB1 was confirmed, and simultaneous regulation of both could effectively inhibit the EMT process in gemcitabine-resistant pancreatic cancer." (PMID 37737908, 2023). "Moreover, miR-128 regulates the infiltration of antitumor immune cells, including dendritic cells (DCs), CD8 + T cells, and NKT cells, in the immune microenvironment via the ZEB1/CD47 axis and epithelial-mesenchymal transition, ultimately inhibiting pancreatic cancer growth and metastasis." (PMID 34968167, 2022). "For example, ZEB1 could be relevant in the early tumorigenesis of pancreatic carcinoma, and in non-epithelial tumors such as melanoma." (PMID 35682554, 2022). "As observed in pancreatic tumor xenograft models, siRNA-mediated knockdown of DCLK1 or downregulation by a kinase inhibitor XMD8-92 leads to the decreased expression of angiogenic markers/vascular endothelial growth factor (VEGF) receptors (VEGFR1 and VEGFR2) and EMT-TFs ZEB1, ZEB2, Snail, and Slug." (PMID 34453639, 2021). "The results displayed that, compared with the adjacent normal tissues, the expression pattern of ZEB1 was increased in the pancreatic cancer tissues, while a negative correlation was depicted between the ZEB1 expression pattern and the expression pattern of LINC00472." (PMID 34363438, 2021). "Another hypothesis is that EMT-TFs expression is organ (and therefore) tumor specific, e.g., Snai1 and Twist1 are not necessary in mouse model of pancreatic cancer, while Zeb1 knock-out reduces metastasis of about 30%." (PMID 34768901, 2021).
pancreatic cancer (continued). "Reversing EMT by silencing of Zeb-1 not only restored the expression of typical epithelial marker genes but also increased the sensitivity of the cells to therapeutic agents, suggesting that Zeb-1 and other EMT regulatory factors maintain drug resistance in human pancreatic cancer cells." (PMID 31514451, 2019). "In this regard, Snai1 and Twist1 may indeed be dispensable for metastatic progression of PDAC, but the critical role of the EMT activator Zeb1 in this cancer type means that we cannot dismiss EMT as a fundamental event preceding invasion and metastasis of pancreatic cancer." (PMID 29903049, 2018). "Experimental research proved that Zinc finger E-box binding homeobox 1 (ZEB1) is a crucial EMT promoter and inhibits expression of the microRNA-200 (miR-200) family and miR-203, resulting in the maintenance of stemness and EMT activation in colorectal and pancreatic cancer." (PMID 27006664, 2016). "Especially, in pancreatic cancer, the expression of EMT markers such as Ncadherin, Vimentin, and transcription factors including ZEB1, Snail, and Twist have been increased in surgically resected pancreatic cancer sepecimens but not in the normal noncancerous pancreatic tissue." (PMID 27793006, 2016). "Importantly, ZEB1, the transcription factor for EMT exerting critical roles in malignant progression of cancers including pancreatic cancer, might be potential target of miR-652 basing on bioinformatics prediction." (PMID 26498682, 2015). "Zeb1 expression in PDAC also correlated with advanced tumor grade and worse outcomes and was shown to be primarily responsible for the acquisition of an EMT phenotype, along with increased migration and invasion in response to NF-κB signaling in pancreatic cancer cells." (PMID 24062980, 2013). "The negative feedback loop between ZEB1 and members of the miR-200 family could also be demonstrated for pancreatic cancer cell lines." (PMID 24281177, 2010). "According to a recent study, ZEB1 is not expressed in normal pancreatic tissue and only weakly in well-differentiated pancreatic carcinoma, whereas it is strongly expressed in dedifferentiated pancreatic carcinoma." (PMID 24281218, 2010). "Moreover, single Zeb1+ tumor cells with a spindle-like morphology that had delaminated from PanIN were identified in adjacent stroma and also in the circulation and the liver of mice without frank pancreatic tumor development." (PMID 34771695, 2021). "Several studies could show that knockdown of the EMT‐TF ZEB1 is sufficient to elicit MET in vitro in carcinoma cell lines of different entities and that depletion of Zeb1 in a genetic mouse model of pancreatic cancer fixes the tumor cells in an epithelial MET state." (PMID 34459003, 2021). "The results indicated a negative effect of high ZEB-1 expression on OS (univariable analysis) in patients with colorectal cancer (pooled HR: 1.80; 95% CI: 1.28–2.54), esophageal squamous cell carcinoma (pooled HR: 1.71; 95% CI: 1.38–2.13) and pancreatic cancer (pooled HR: 1.63; 95% CI: 1.19–2.23)." (PMID 31248382, 2019). "(−)-epigallocatechin-3-gallate (EGCG) is a compound without known target, but in cultured pancreatic cancer cells it simultaneously inhibits expression of Hedgehog pathway components, the EMT markers Snail, Slug, and ZEB1, and the pluripotency factors Nanog, c-MYC, and OCT-4." (PMID 24213498, 2012).